LMNA (lamin A/C)
Diseases named in the same sentence as LMNA in open-access papers (continued):
Sharing a sentence is not in itself a finding about the gene and the disease.
genetic disorder (40 papers, 2011 to 2025). "Background/Objectives: Hutchinson–Gilford progeria syndrome (HGPS) is a rare genetic disorder that cause premature aging due to LMNA mutations and progerin accumulation." (PMID 40310235, 2025). "These non-LMNA mutations are known to cause genetic diseases when present in the germline, with a similar effect on their respective protein as the LMNA mutation on the lamin A protein." (PMID 40495018, 2025). "Hutchinson‐Gilford progeria syndrome (HGPS) is a rare genetic disorder caused by a mutation in the LMNA gene that provokes the synthesis of progerin, a mutant version of the nuclear protein lamin A that accelerates aging and precipitates death." (PMID 39479939, 2025). "Hutchinson–Gilford Progeria Syndrome (HGPS) is an extremely rare genetic disorder that causes accelerated aging, due to a pathogenic variant in the LMNA gene." (PMID 39273272, 2024). "Progeria syndrome is a rare genetic disorder caused by a mutation in the LMNA gene, which encodes lamin A/C proteins that play a crucial role in maintaining the integrity of the cell nucleus, leading to premature aging." (PMID 39416800, 2024). "Recent research into laminopathic lipodystrophies—rare genetic disorders caused by mutations in the LMNA gene—has greatly expanded our knowledge of their complex pathology and metabolic implications." (PMID 39125589, 2024). "Hutchison-Gilford progeria syndrome (HGPS) is a rare genetic disease caused by a mutation in LMNA, the gene encoding A-type lamins, leading to premature aging with severely reduced life span." (PMID 39571160, 2024). "Hutchinson–Gilford Progeria Syndrome (HGPS) is a rare genetic disorder caused by an autosomal dominant mutation in the LMNA gene resulting in the accumulation of a truncated Lamin A version called progerin." (PMID 37174632, 2023). "Hutchinson–Gilford progeria syndrome (HGPS) is an extremely rare genetic disorder caused by the mutant protein progerin, which is expressed by the abnormal splicing of the LMNA gene." (PMID 37759521, 2023). "Hutchinson–Gilford Progeria Syndrome (HGPS) is an extremely rare genetic disorder caused by mutations in the LMNA gene and characterized by premature and accelerated aging beginning in childhood." (PMID 35045206, 2022). "The discovery that several genetic diseases are caused by mutations in the LMNA gene has resulted in a reassessment of the function of the nuclear lamina." (PMID 33036437, 2020). "Mutations in LMNA gene are frequently identified in patients suffering from a genetic disorder known as Hutchison–Gilford progeria syndrome (HGPS), providing an ideal model for the understanding of the mechanisms of aging." (PMID 32813328, 2020). "Mutations in LMNA, coding for lamin A and C, are the cause of approximately a dozen inherited diseases, collectively called “laminopathies”, that were initially defined based on clinical signs and symptoms." (PMID 28854936, 2017). "Dunnigan-type familial partial lipodystrophy 2 (FPLD2; MIM: #151660) is a genetic disease caused by mutations in lamin A/C (LMNA) gene (ENSG00000160789)." (PMID 27504462, 2016). "Hutchinson-Gilford progeria syndrome (HGPS) is a genetic disorder caused by mutations in the lamin A/C gene (LMNA), a component of the nuclear lamina." (PMID 21738662, 2011). "Hutchinson-Gilford progeria syndrome (HGPS) is a genetic disorder displaying features reminiscent of premature senescence caused by germline mutations in the LMNA gene encoding lamin A and C, essential components of the nuclear lamina." (PMID 21738662, 2011). "Hutchinson-Gilford progeria syndrome (HGPS) is an ultra-rare genetic disease caused by a heterozygous de novo point mutation in the LMNA gene (c.1824C > T/p.G608G in most patients) that provokes the production and accumulation of a truncated form of the prelamin A protein called progerin." (PMID 35752705, 2023).
genetic disorder (continued). "The premature ageing disorder Huntchinson–Gliford Progeria Syndrome (HGPS) is an extremely rare genetic disorder caused by a de novo point mutation in exon 11 of the LMNA gene, leading to the increased expression of a truncated splicing mutant of lamin A protein named progerin." (PMID 31795382, 2019). "Given the importance and multiple functions of lamina A and lamina C in maintaining the structure and function of the cell nucleus, it would be expected that mutations in the LMNA gene could cause different types of genetic disorders, with different phenotypes." (PMID 38808865, 2024). "Emery–Dreifuss syndrome is a rare genetic disease, caused by mutations of emerin (EMD) and lamin A/C (LMNA) genes, and can be autosomal dominant or recessive." (PMID 34356086, 2021). "Although mutations in the human EMD gene are most closely tied to the genetic disorder EDMD1, similar phenotypes arise from mutations in genes coding for interacting proteins, such as LMNA, SYNE1, SYNE2, and TMEM43." (PMID 30871242, 2019). "Hutchison-Gilford progeria syndrome (HGPS; OMIM 176670) is a rare human genetic disorder linked with a subset of specific mutations in the LMNA gene, coding for lamin A and lamin C proteins." (PMID 30691039, 2019). "Lamin A/C (LMNA/C) is one of the principal components of the envelope and one of the most studied genes since it harbors hundreds of relevant mutations, many of which are linked to the Hutchinson–Gilford syndrome, an extremely rare, progressive genetic disorder that causes children to age rapidly." (PMID 34471128, 2021).
myopathy (23 papers, 2013 to 2025). A disease of the muscle in which the muscle fibers do not function properly. "For example, a defect in phosphorylation of Lamin A at Ser458 due to LMNA gene mutations has been associated with myopathy." (PMID 39615679, 2025). "The canonical intrinsic splicing mutation in the LMNA gene would cause cardiac involvement with variable myopathy." (PMID 38259623, 2023). "SEPN1-RM predominantly manifests as cervico-dorsal spinal rigidity that differs from the rigid spine in myopathies caused by mutations in LMNA, EMD, COL6 (Bönnemann, 2011), or RYR1." (PMID 35368679, 2022). "Mutations causing myopathy are distributed all along the LMNA gene, and are the most common (60% of laminopathies), whilst the 75% of the mutations causing lipodystrophies affect the IgG-like domain." (PMID 29557732, 2018). "Similar FTD is also observed in other LMNA related myopathies such as limb-girdle muscle dystrophy (LMNA mutation p.T27I)." (PMID 28441765, 2017). "In summary, overlapping syndromes deepen the need to actively seek the presence of LMNA mutations in subjects with clinical features of partial lipodystrophy, cardiac abnormalities, or certain types of myopathy, in order to prevent, as far as possible, their potentially lethal consequences." (PMID 29557732, 2018). "However, LMNA mutations were identified in about half of a small cohort of Japanese patients suspected to have an inflammatory myopathy presenting before the age of two years, with some benefit from steroids in four out of the eight treated cases." (PMID 27529282, 2016). "DCM is one such myopathy where mutations in LMNA are major causative factors." (PMID 24386194, 2013). "For probands A1, A2, and B6, we previously found mutations in myopathy-related genes in FKRP, LMNA, and CCDC78, respectively." (PMID 34720847, 2021). "We suggested that LMNA gene related myopathies should be considered in young stroke patients with long-standing myopathic features." (PMID 23360689, 2013). "However, LMNA mutant nuclei exhibited greater nuclear atypia and fragmentation compared to the control fibroblasts from an unrelated myopathy without LMNA mutations." (PMID 29610677, 2018). "Other cohort was published in 2014, and included 78 cases diagnosed with LMNA-related myopathies (EDMD, 21%; L-CMD, 33%; LGMD1B, 46%)." (PMID 37035729, 2023).
infection (14 papers, 2008 to 2024). The state of being infected such as from the introduction of a foreign agent such as serum, vaccine, antigenic substance or organism. "At later times post‐infection, phosphorylation of lamin A/C mediated by virus‐encoded kinases (β‐ and γ‐herpesviruses) or cellular kinases (α‐herpesviruses) leads to disintegration of the nuclear lamina, facilitating subsequent capsid escape from the nucleus." (PMID 39288210, 2024). "Although the level of lamin A/C in cells lysed at 24 hpi was slightly elevated compared with that in mock‐infected cells, at later times post‐infection, the amount of lamin A/C decreased gradually up to 61% at 40 hpi compared with that in mock‐infected cells." (PMID 39288210, 2024). "Vero cells were infected with HSV-2 strains containing mCherry (mCh) fused to the capsid protein VP26, stained for the nuclear lamina protein, lamin A/C, and DNA (Hoechst 33342), and examined by confocal microscopy at 18 hours post infection (hpi)." (PMID 38039340, 2023). "We observed that lamin A/C mRNA abundance significantly increased 4 days post infection and reached a ~10-fold increase 28 days post infections, when EBV+ B cells exhibit LCL physiology and the Type III latency gene expression program." (PMID 35421198, 2022). "This hypothesis is consistent with published transcriptional profiling of EBV infection of B cells showing that in the pre-latent viral phase of the infection, the peak of lamin A/C expression coincides with reduced expression of EBNA2, BHRF1, and EBNA-LP." (PMID 35421198, 2022). "Interestingly, work from the Gewurz laboratory showed that LMP1 is expressed 4 days post infection of primary B cells, which temporally coincides with expression of lamin A/C in EBV-infected B cells in our analysis." (PMID 35421198, 2022). "Although the absence of lamin A/C does not affect the formation of VRCs, it negatively influences virus gene expression and genome replication, which results in the deceleration of the virus replication cycle in the early phases of infection." (PMID 39288210, 2024).
peripheral neuropathy (10 papers, 2011 to 2025). A disorder affecting the peripheral nervous system. "More than 10 different clinical syndromes including diseases of striated muscle, lipodystrophy syndromes, peripheral neuropathy, or accelerated aging are caused by various mutations in the LMNA gene." (PMID 22072982, 2011).
degenerative diseases (5 papers, 2008 to 2026). "All A-type lamins are encoded by LMNA by alternative splicing, and mutations in this gene give rise to 16 tissue-specific degenerative diseases collectively known as laminopathies." (PMID 21364987, 2011).
metabolic disease (5 papers, 2017 to 2023). A congenital disorder (due to inherited enzyme abnormality) or acquired (due to failure of a metabolically important organ) disorder resulting from an abnormal metabolic process. "Mutations in the human LMNA gene cause numerous diseases, including metabolic diseases, accelerated aging disorders and muscle diseases." (PMID 34383046, 2021). "Mutations in lamin A (LMNA) are responsible for a variety of human dystrophic and metabolic diseases." (PMID 31833196, 2020). "Our study identified novel LMNA variants predicted to perturb specific regions of lamin A/C polypeptides, including atomic ‘features’ on the Ig-fold surface distinct from those previously implicated in striated muscle disease, progeria or metabolic disorder." (PMID 28663758, 2017). "Mutations in LMNA genes are associated with aging disorders as well as metabolic diseases." (PMID 34383046, 2021). "These two studies support the hypothesis that LMNA mutations in the general population contribute to metabolic disease risk." (PMID 28663758, 2017).
neuromuscular disease (3 papers, 2008 to 2024). "The clinical evolution was similar but delayed in one of the twins, suggesting that the cause of disease was the deleterious variant in the LMNA gene, identified using an NGS approach, in concordance with recent studies focused on the diagnosis of neuromuscular diseases." (PMID 38892025, 2024). "A meta-analysis of clinical characteristics of LMNA mutation carriers revealed that LMNA mutations carry a high risk of sudden death, and that this risk does not differ between subjects with predominantly cardiac or neuromuscular disease." (PMID 19099557, 2008).
autosomal dominant disease (2 papers, 2022 to 2024). Autosomal dominant form of disease. "HGPS is an autosomal dominant disease caused by a de novo mutation of LMNA gene, encoding A-type lamins, resulting in the truncated form of pre-lamin A called progerin." (PMID 39353941, 2024).
bone disorder (1 paper, 2018). "Two hot spots in LMNA gene are linked to syndromes featuring bone disorders, the c.C1824T mutation (p.G608G) associated with HGPS and a few cases of RD, and the c.1580G>A mutation (p.R527H), linked to MADA." (PMID 29854317, 2018).
brain disorder (1 paper, 2021). A disease affecting the brain or part of the brain. "Interestingly, out of five key SG genes that showed a high number of associations with brain disorders, three genes, namely LMNA (k = 14), DCTN1 (k = 8), and ALDH18A1 (k = 4), also play important roles in disorders having a major impact on lungs and respiratory ability of the patients." (PMID 34832615, 2021). "The network revealed that the majority of the disorders are linked with DYNC1H1 (k = 91), LMNA (k = 86), FMR1 (k = 74), DCTN1 (k = 57), and ALDH18A1 (k = 54) genes and showed interactions with multiple brain disorders." (PMID 34832615, 2021).
neurological disorders (1 paper, 2022). "Mutations and deletions in the LMNA gene have been shown previously to promote oxidative stress, premature ageing and neurological disorders." (PMID 35721517, 2022).
vasculopathy (1 paper, 2005). "We tested not only the hypothesis that alleles of LMNA or KLOTHO would be associated with premature CAD (a population enriched for inherited contributions), but also pre-specified that such premature vasculopathy might be associated with an excess of homozygosity at the LMNA locus." (PMID 16262891, 2005).
LMNA also shares sentences with these, for which no sentence is quoted: limb-girdle muscular dystrophy type 1B (11 papers); cardiovascular disease (8); generalized lipodystrophy (6); cardiac arrhythmias (4); Duchenne muscular dystrophy (4); Glucose intolerance (4); hypertrophic cardiomyopathy (4); lymphoma (4); Stroke (4); Brugada syndrome (3); cardiac conduction defect (3); familial hypercholesterolemia (3); sick sinus syndrome (3); thyroid cancer (3); acanthosis nigricans (2); Alzheimer disease (2); ataxia telangiectasia (2); atrial standstill (2); cardiac sarcoidosis (2); catecholaminergic polymorphic ventricular tachycardia (2); Charcot-Marie-Tooth disease type 2B1 (2); Charcot-Marie-Tooth neuropathy (2); chronic kidney disease (2); death (2); familial atrial fibrillation (2); genetic lipodystrophy (2); Hirsutism (2); Holt-Oram syndrome (2); Hypergonadotropic hypogonadism (2); Hyperinsulinemia (2).
A further 121 diseases each share a sentence with LMNA in 2 papers or fewer.